ZNF570 (zinc finger protein 570)
Description:
May be involved in transcriptional regulation.
Synonyms: FLJ30791
Tractability: PROTAC: ubiquitination databases record sites on it.
Gene: Protein-coding gene on chromosome 19 (37,467,508 to 37,488,652, forward strand). Ensembl gene ENSG00000171827.
Subcellular location: Nucleus
Subcellular location (Human Protein Atlas): Nucleoplasm
Pathways (Reactome):
Gene expression (Transcription): Generic Transcription Pathway
Gene Ontology:
Molecular function: DNA-binding transcription factor activity, RNA polymerase II-specific; RNA polymerase II cis-regulatory region sequence-specific DNA binding
Biological process: regulation of transcription by RNA polymerase II; regulation of DNA-templated transcription
Cellular component: nucleus
Genetic constraint (gnomAD): Loss-of-function variants: 13 observed, 21.43 expected, observed/expected ratio (o/e) 0.61, 90% interval 0.39 to 0.96. The upper end of that interval is the gene's LOEUF score, 0.96, which puts it in group 4 of 6, group 1 being the genes least tolerant of losing a copy. Missense variants: 559 observed, 658.38 expected, observed/expected ratio (o/e) 0.85, 90% interval 0.79 to 0.91. Synonymous variants: 202 observed, 218.31 expected, observed/expected ratio (o/e) 0.93, 90% interval 0.82 to 1.04.
Homologues: Orthologues: chimpanzee ZNF570 (100% identical), macaque ZNF570 (99% identical), pig ZNF570 (91% identical), rabbit ZNF570 (90% identical), guinea pig ZNF570 (89% identical), mouse Zfp39 (44% identical), rat Zfp39 (44% identical). Paralogues in human: ZNF583 (69% identical), ZNF480 (45% identical), ZNF304 (40% identical), ZNF551 (40% identical), ZNF792 (40% identical), ZNF79 (39% identical), ZNF256 (38% identical), ZSCAN2 (38% identical), ZSCAN20 (38% identical), ZNF587B (38% identical), ZNF549 (37% identical), ZNF418 (37% identical), and 26 more.
Diseases named in the same sentence as ZNF570 in open-access papers:
ZNF570 is named in the same sentence as 1 disease in open-access papers, as found by Europe PMC text mining. Sharing a sentence is not in itself a finding about the gene and the disease. The quoted sentences say what the papers report.
cancer (1 paper, 2019). A tumor composed of atypical neoplastic, often pleomorphic cells that invade other tissues. "Cancer development was observed by the modulation of genes involved in cell death (HIST1H1T, CASP14, and DNAJC3), cancer related genes (WNT8A and CASC8), gene expression (transcription) (ZNF570 and ZFP42), and metabolism of proteins (CALB2 and KLHDC3)." (PMID 31797963, 2019).